RNF166 (ring finger protein 166)
Description:
E3 ubiquitin-protein ligase that promotes the ubiquitination of different substrates. In turn, participates in different biological processes including interferon production or autophagy. Plays a role in the activation of RNA virus-induced interferon-beta production by promoting the ubiquitination of TRAF3 and TRAF6. Also plays a role in the early recruitment of autophagy adapters to bacteria. Mediates 'Lys-29' and 'Lys-33'-linked ubiquitination of SQSTM1 leading to xenophagic targeting of bacteria and inhibition of their replication.
Synonyms: MGC2647; MGC14381
Tractability: Antibody: the Human Protein Atlas places it where antibodies can reach. PROTAC: ubiquitination databases record sites on it; its protein half-life has been measured.
Gene: Protein-coding gene on chromosome 16 (88,696,495 to 88,706,424, reverse strand). Ensembl gene ENSG00000158717.
Subcellular location: Cytoplasm
Subcellular location (Human Protein Atlas): Nucleoplasm; Cytosol; Plasma membrane
Gene Ontology:
Molecular function: protein binding; ubiquitin protein ligase activity
Biological process: protein polyubiquitination; ubiquitin-dependent protein catabolic process; protein ubiquitination
Cellular component: cytoplasm
Genetic constraint (gnomAD): Loss-of-function variants: 19 observed, 21.47 expected, observed/expected ratio (o/e) 0.89, 90% interval 0.62 to 1.3. The synonymous counts are far from expectation, so gnomAD's model fits this gene poorly and the ratio says little. Missense variants: 346 observed, 278.76 expected, observed/expected ratio (o/e) 1.24, 90% interval 1.14 to 1.36. Synonymous variants: 171 observed, 116.59 expected, observed/expected ratio (o/e) 1.47, 90% interval 1.29 to 1.66.
Homologues: Orthologues: chimpanzee RNF166 (100% identical), macaque RNF166 (99% identical), guinea pig RNF166 (99% identical), mouse Rnf166 (99% identical), dog RNF166 (86% identical), zebrafish rnf166 (82% identical), tropical clawed frog rnf166 (81% identical), rat Rnf166 (81% identical), pig RNF166 (58% identical). Paralogues in human: RNF114 (41% identical), RNF138 (32% identical), RNF125 (31% identical), RNF180 (22% identical).
Diseases named in the same sentence as RNF166 in open-access papers:
RNF166 is named in the same sentence as 7 diseases in open-access papers, as found by Europe PMC text mining. Sharing a sentence is not in itself a finding about the gene and the disease. The quoted sentences say what the papers report.
colorectal cancer (1 paper, 2024). A primary or metastatic malignant neoplasm that affects the colon or rectum. "In this study, we uncover the involvement of an upregulated E3 ubiquitin ligase called RNF166, which destabilizes angiomotins, activates YAP, and is associated with a poor prognosis in colorectal cancer patients." (PMID 38480683, 2024). "Additionally, YAP-5SA, a constitutively active form of YAP, rescues colorectal cancer progression following knockdown of RNF166." (PMID 38480683, 2024).
Stroke (1 paper, 2023). Sudden impairment of blood flow to a part of the brain due to occlusion or rupture of an artery to the brain. "Co-expressed hub genes of EIF4E3, ZNF595, ZNF700, MATR3, ACKR4, ANXA3, SEPSECS-AS1, and RNF166 were significantly associated with AF-related stroke." (PMID 36952494, 2023). "Hub genes EIF4E3, ZNF595, ZNF700, MATR3, ACKR4, ANXA3, SEPSECS-AS1, and RNF166 have potential as novel biomarkers and therapeutic targets in AF-related stroke." (PMID 36952494, 2023). "The hub genes of EIF4E3, ZNF595, ZNF700, MATR3, ACKR4, ANXA3, SEPSECS-AS1, and RNF166 may link AF and secondary stroke." (PMID 36952494, 2023). "Based on the results of DEG3 and ROC curves in GSE66724 and GSE58294, we filtered eight hub genes of AF-related stroke (AUC > 0.8), including EIF4E3, ZNF595, ZNF700, MATR3, ACKR4, ANXA3, SEPSECS-AS1, and RNF166." (PMID 36952494, 2023). "The expression of MATR4, ACKR4, RNF166, and miR-198 in AF-related stroke patients was lower than those in AF patients without stroke." (PMID 36952494, 2023).
Varicose veins (1 paper, 2021). Enlarged and tortuous veins. "Using a broad GWAS catalog, we found one of our dynamic eQTL SNPs (rs8053350) to be associated with varicose veins, and the level of RNF166 expression." (PMID 33554857, 2021).
viral infection (1 paper, 2015). "Third, RNF166 interacted with endogenous TRAF3 and TRAF6, and these interactions were enhanced upon viral infection." (PMID 26456228, 2015).
tumor (1 paper, 2021). "Taken together, the correlation between RNF166 and tumor prognosis is first reported in our study." (PMID 34760926, 2021).
RNF166 also shares sentences with these, for which no sentence is quoted: cancer (1 paper); infection (1).